ENSG00000252582
Synonyms: LOC124900284
Gene: Small nucleolar RNA gene on chromosome 9 (131,021,168 to 131,021,306, reverse strand). Ensembl gene ENSG00000252582.
Gene Ontology:
Biological process: RNA processing
Cellular component: nucleolus
Homologues: Paralogues in human: SNORA31B (77% identical), SNORA31 (63% identical).